SNORA72 (Small nucleolar RNA SNORA72 )
Synonyms: LOC124900519
Gene: Small nucleolar RNA gene on chromosome 2 (139,511,424 to 139,511,555, forward strand). Ensembl gene ENSG00000206901.
Gene Ontology:
Biological process: RNA processing
Cellular component: nucleolus
Homologues: Orthologues: chimpanzee SNORA72 (100% identical), macaque SNORA72 (89% identical), pig SNORA72 (85% identical), dog SNORA72 (83% identical), guinea pig SNORA72 (83% identical), rat LOC120093944 (80% identical), rat LOC120095384 (80% identical), guinea pig SNORA72 (80% identical), mouse Gm24523 (80% identical), rabbit SNORA72 (80% identical), rat LOC120098350 (77% identical), tropical clawed frog SNORA72 (59% identical), and 1 more. Paralogues in human: SNORA72 (86% identical), SNORA72 (81% identical), SNORA72 (77% identical), SNORA72 (76% identical), SNORA72 (71% identical), SNORA72 (48% identical).
Diseases named in the same sentence as SNORA72 in open-access papers:
SNORA72 is named in the same sentence as 1 disease in open-access papers, as found by Europe PMC text mining. Sharing a sentence is not in itself a finding about the gene and the disease. The quoted sentences say what the papers report.
ovarian carcinoma (3 papers, 2020 to 2022). A malignant neoplasm originating from the surface ovarian epithelium. "For instance, SNORA72 displays high expression in ovarian cancer and promotes the maintenance of ovarian cancer stem cell stemness by activating the Notch1/c‐Myc pathway." (PMID 34047477, 2021). "SNORA72 promotes the self-renewal and migration of ovarian cancer cells and is vital for the maintenance of stemness in OCSCs." (PMID 33224949, 2020). "The overexpression of SNORA72 increased ovarian cancer cells’ self-renewal and migration abilities." (PMID 36078146, 2022). "Thus, SNORA72 plays an important role in the stemness transformation and maintenance of ovarian cancer cells." (PMID 33224949, 2020).